INS (insulin)
Diseases named in the same sentence as INS in open-access papers (continued):
Sharing a sentence is not in itself a finding about the gene and the disease.
diabetes (continued). "There was greater prior CVD, family history of diabetes, and use of diabetes medications (insulin and metformin) at baseline with higher HbA1c." (PMID 37978826, 2024). "An important advance achieved in the present study was the understanding of the renoprotective effects of lycopene + 1 U/day insulin in diabetes." (PMID 38892513, 2024). "Compared to traditional diabetes medications like sulfonylureas and insulin, GLP-1 receptor agonists GLP-1RAs and SGLT2 inhibitors demonstrate stronger evidence for reducing mortality." (PMID 39452297, 2024). "Type 2 diabetes (T2D), which accounts for over 90% of diabetes cases, is characterized by insulin resistance and impaired insulin secretion, leading to dysregulated glucose and lipid metabolism." (PMID 39599684, 2024). "A greater proportion of participants in the NSTDR group (86%) controlled their diabetes with either diet or tablets compared to the 53% in the STDR group who were on either insulin or a combination of insulin and tablets or diet control) treatment." (PMID 38167028, 2024). "This axis regulates glucose homeostasis under conditions that drive the pathological hallmarks of diabetes, including tissue resistance to insulin, by governing both insulin production and the insulin sensitivity of adipose tissue." (PMID 39033139, 2024). "During the first trimester, we optimized the insulin regime and created an interdisciplinary team of obstetrics and diabetes specialist." (PMID 38958733, 2024). "In the unadjusted analyses and adjustment for age, sex, and body fat (%), insulin AUC180-min, AUC240-min, iAUC180-min, and iAUC240-min were all independently associated with increased risk of diabetes (p-values < 0.01)." (PMID 38987291, 2024). "Ectopic overexpression of Sox9 in beta cells leads to cellular dedifferentiation and diabetes, with stunted expression of genes required for appropriate insulin secretion." (PMID 38238288, 2024). "Diabetes mellitus (DM) is a common metabolic disease resulting from a defect in either insulin secretion or insulin action, or a combination of both." (PMID 39595508, 2024). "TZD has shown effects on insulin sensitivity at the Akt level in several models of obesity and diabetes, demonstrating the importance of this kinase in glucose metabolism." (PMID 38248457, 2024). "For the PE, she was treated with systemic thrombolysis followed by a standard oral factor Xa inhibitor; for her new onset of diabetes, the patient was started on glargine and lispro insulin." (PMID 39156451, 2024). "Insulin resistance (IR), due to a blunted response to insulin activity, is closely associated with the development and pathogenesis of metabolic dyshomeostasis, including impaired fasting glucose (IFG) and type 2 diabetes mellitus (T2DM)." (PMID 38410697, 2024). "Diabetes is a complex multifactorial metabolic syndrome characterized by hyperglycemia resulting from insufficient insulin secretion or insulin resistance, with 90% of diabetic patients diagnosed with diabetes mellitus type 2 (T2DM)." (PMID 38978780, 2024). "Despite the development of numerous non-insulin glucose-lowering agents for managing diabetes, controlling target blood glucose levels remains challenging and often results in undesirable side effects." (PMID 39275157, 2024). "The use of antidiabetic medications, including insulin, but excluding metformin, was more prevalent in subjects with a longer duration of diabetes." (PMID 38366387, 2024). "vaha mutants are defective in fat amplified insulin secretion and exhibit hyperglycemia like human diabetics." (PMID 38782979, 2024). "In terms of the choice of treatment regimens, the Chinese Diabetes Society guideline and expert consensus on glycemic control of hospitalized patients have fully acknowledged the significant role of insulin therapy and recommend it as the preferred option." (PMID 39280993, 2024).
diabetes (continued). "In order to treat diabetes, transdermal insulin delivery patches are utilized to transfer insulin through the skin and into the bloodstream." (PMID 39458987, 2024). "Insulin resistance is a critical pathogenic element in a variety of metabolic diseases, such as type 2 diabetes mellitus, distinguished by diminished sensitivity of insulin-sensitive tissues to normal insulin levels physiologically." (PMID 39807459, 2024). "After this intervention, the patient required insulin therapy for the management of post-surgical diabetes mellitus." (PMID 39104820, 2024). "Taking diabetes as an example, an imbalance where the demand for insulin (functional requirement) exceeds its supply leads to hyperglycaemia." (PMID 38729991, 2024). "A large number of preclinical studies have recently revealed that peripheral CB1 can promote energy storage, affect lipid metabolism and insulin sensitivity, and significantly contribute to the pathogenesis of obesity, metabolic syndrome, and diabetes." (PMID 38360685, 2024). "The majority (88.8%) of patients were on medication for diabetes (oral hypoglycemic agents (OHAs) and/or insulin), and most reported having one or more comorbidities." (PMID 39438811, 2024). "In the 2 years after pregnancy, diabetes progressively deteriorated with a variable HbA1c (7.3-8.6%) during diet, insulin treatment (3 UI/kg/die), SGLT2 inhibitor, and semaglutide (0.25 mg/weekly)." (PMID 39479521, 2024). "By negatively affecting pancreatic beta cell function and insulin sensitivity, promoting inflammation, and contributing to increased visceral fat, smoking significantly increases the incidence of clinical diabetes." (PMID 38247531, 2024). "Chronic inflammation can damage pancreatic beta cells, impairing insulin production and contributing to the development of diabetes." (PMID 39338165, 2024). "Magnesium, a key regulator of vascular tone, glucose metabolism, and insulin sensitivity, plays a crucial role in mitigating gestational hypertension and diabetes, a point this review underscores." (PMID 39203767, 2024). "Management involved the initiation of multiple daily insulin injections for diabetes control, gynecological evaluation for MRKH syndrome, and multidisciplinary care for associated complications." (PMID 38671621, 2024). "Other highly correlated biomarkers such as HbA1c, GHSA, and insulin are now becoming important research subjects in the diagnosis and monitoring of diabetes." (PMID 39091901, 2024). "Relating comorbidity and patient characteristics, only diabetes mellitus, which required treatment with insulin, affected mortality." (PMID 38268012, 2024). "This increase in SCFA production can stimulate the production of GLP1, a hormone that promotes insulin secretion, improves glucose homeostasis, reduces inflammation, increases satiety, and alleviates type 2 diabetes mellitus." (PMID 38541047, 2024). "The analysis indicated alteration of many metabolic pathways related to diabetes, such as insulin and glucagon signaling pathways and regulation of lipolysis in adipocytes." (PMID 38880916, 2024). "Adiponectin is an insulin‐sensitizing adipocyte with diabetes‐preventive properties, and a decrease in adiponectin values results in adiposity and insulin resistance." (PMID 39479712, 2024). "In the included case reports and case series, which were mainly cross-sectional, most patients diagnosed with HNF1B-diabetes or MD seem to have commenced insulin treatment at some stage." (PMID 39025920, 2024). "Conceivably, the defects in insulin secretion are likely to be a continuous process that begins long before the onset of overt diabetes." (PMID 39221169, 2024). "This type of diabetes is characterized by insulin resistance, which leads to increased insulin production and, eventually, atrophy in pancreatic beta cells, reducing insulin secretion." (PMID 39519516, 2024).
diabetes (continued). "Specifically, the induction of Nrf2 through Keap1-conditional knockout in pancreatic β-cells was found to suppress oxidative damage in pancreatic islets and significantly restore insulin secretion in the context of diabetes." (PMID 38671848, 2024). "The evidence for the efficacy of non-insulin therapies was stronger for the relapse phase of diabetes later in life, where most cases appeared to benefit from a variety of non-insulin therapies, with most not requiring insulin." (PMID 39025920, 2024). "Many conventional diabetes medications, such as Metformin, primarily focus on a single target, such as insulin sensitivity or hepatic glucose production." (PMID 39000103, 2024). "Diabetes mellitus, often a complication of acromegaly, arises mainly from insulin resistance and pancreatic β-cell dysfunction induced by elevated levels of GH and IGF-1." (PMID 39331882, 2024). "Insulin pumps can help people with diabetes for management of insulin-dependent diabetes and lower the risks of complications." (PMID 39238969, 2024). "The average glucose trend declined for patients receiving any of these TKIs, and almost half of the patients with diabetes were able to completely discontinue their insulin therapy." (PMID 39659385, 2024). "A previous study showed that it reduced blood glucose concentrations in rats and mice in an experimentally induced model of diabetes and preserved β-cell numbers in the pancreas and insulin sensitivity." (PMID 38534744, 2024). "The patient presented with type 2 diabetes mellitus for at least 15 years and was treated first with oral antidiabetics and then insulin analog therapy (insulin aspart and insulin glargine)." (PMID 39071705, 2024). "After exclusion of individuals with diabetes or missing insulin measures, 1166 participants formed the population of the present study." (PMID 39661465, 2024). "Diabetes mellitus (DM) is characterized by impaired glucose and insulin metabolism, resulting in chronic hyperglycemia." (PMID 38212345, 2024). "Decreases in the serum level of IGF1, similar to insulin, are positively related to the occurrence of type I and 11 diabetes." (PMID 39590301, 2024). "These insights provided essential clues about the biological underpinnings of diabetes, setting the stage for the discovery of insulin in the 20th century and transforming diabetes from an often fatal disease into a much more manageable condition." (PMID 39691108, 2024). "People managing diabetes have a broad variety of options when it comes to insulin administration, with each kind offering unique advantages and considerations." (PMID 39065641, 2024). "Type 2 Diabetes (T2D) is a common form of diabetes mellitus characterized by hyperglycemia, impaired insulin sensitivity and insufficient insulin levels." (PMID 38460073, 2024). "By initiating proactive diabetes management early, it is possible to markedly improve β-cell function as well as insulin sensitivity, possibly allowing the therapy to be stopped after a few months." (PMID 39634998, 2024). "Islets from vaccinated mice with progressive disease displayed significantly higher percentages of insulin positive cells compared to islets from vaccinated mice with acute onset of diabetes (Wilch’s t test, p < 0.0001)." (PMID 38781241, 2024). "The ML algorithms identified diabetes duration, insulin usage, age, and tyrosine as the most important factors of both DKD and DR." (PMID 38546730, 2024). "Regular physical exercise increases glucose uptake in activated muscle, which induces increased insulin sensitivity in diabetics." (PMID 39377072, 2024). "Inflammation is a distinguished clinical manifestation of COVID-19 and type 2 diabetes mellitus (T2DM), often associated with inflammatory dysfunctions, insulin resistance, metabolic dysregulation, and other complications." (PMID 38675414, 2024).
diabetes (continued). "Experiments investigating the effect of inducing endoplasmic reticulum stress in POMC neurons observed inhibition of the activation of the insulin signaling pathway, whereas diabetes-related brain damage improved after inhibiting endoplasmic reticulum stress." (PMID 38818523, 2024). "This technology has established itself in many countries as a standard tool for monitoring glucose in insulin-treated patients with diabetes." (PMID 38370356, 2024). "β-cell regeneration and proliferation are essential for diabetes treatment, restoring insulin production, and managing blood glucose levels." (PMID 39057094, 2024). "PPARγ agonists, such as thiazolidinediones (TZD), act as insulin-sensitizing agents and are currently used in clinical practice for the treatment of diabetes." (PMID 38892571, 2024). "Recommendation: There is insufficient data to recommend or refute the preferential use of insulin or any other medication in HNF1B-diabetes or mitochondrial diabetes." (PMID 39025920, 2024). "As it has been reported that CO improves insulin resistance and the pathophysiology of animal models of diabetes, we expect that CO-RBCs will be effective for these MASH patients as well." (PMID 39163766, 2024). "In our study, the definition of diabetes was based on the reimbursement and redeeming of at least one insulin product or oral antidiabetic agent." (PMID 38904171, 2024). "Insulin secretory capacity is markedly decreased in East Asians with diabetes compared to Westerners." (PMID 40607157, 2024). "People with diabetes using insulin also require self-monitoring blood glucose (SMBG) devices (e.g., meters, strips, continuous monitoring systems) for day-to-day management." (PMID 39361609, 2024). "Diabetes medications included monotherapy with metformin (n=12) and combination therapy with metformin plus insulin and glinide (n=3)." (PMID 38598270, 2024). "These technological advancements have markedly altered how diabetes is managed, particularly through the utilization of real-time glucose data for more precise insulin dose adjustments." (PMID 39519579, 2024). "By helping with diabetic markers, regulating glucose metabolism enzymes, improving insulin sensitivity, and reducing inflammation, it effectively helps in controlling diabetes." (PMID 38496846, 2024). "In this initiative, we harnessed the potential of CGM devices compared to SMBG to improve the management of patients with uncontrolled diabetes who were using 3-4 injections of insulin per day." (PMID 39149659, 2024). "Dysfunction of pancreatic endocrine cells, particularly the failure of β cells to produce insulin, results in diabetes mellitus." (PMID 39105169, 2024). "The exact pathogenesis of GDM is still debated; however, insulin resistance, defined as an impaired response of target cells to insulin, is thought to be a key pathological feature of diabetic pregnancy, similarly to type 2 diabetes mellitus (T2DM)." (PMID 39684804, 2024). "The nature of diabetes is due to an imbalance in glycolipid metabolism as a result of abnormalities in insulin utilization or secretion in the body." (PMID 39633648, 2024). "Concerning the treatment of diabetes more than half of them used insulin in treatment, most of them have complications from diabetes and most of them suffered from chronic diseases." (PMID 38724979, 2024). "A study showed that the body’s sensitivity to insulin was improved and that the incidence of GDM decreased when magnesium supplementation was used for pregnant women at a high risk of diabetes." (PMID 39203767, 2024). "BCP treatment promotes the biosynthesis of arginine, which is the main biological precursor of nitric oxide (NO), and has been described to improve insulin sensitivity in diabetes and obesity." (PMID 39444574, 2024). "Insulin can control glucose homeostasis by stimulating glucose uptake, and is used for the treatment of type 1 diabetes mellitus (T1DM) and advanced type 2 diabetes mellitus (T2DM) in clinical 4-6." (PMID 39310111, 2024).
diabetes (continued). "Diabetes associated with PERK deficiency is attributed to insufficient β-cell proliferation and defective insulin secretion." (PMID 38509524, 2024). "Type 2 diabetes mellitus represents a multifaceted disorder characterized by intricate pathophysiological mechanisms, encompassing diminished insulin secretion, augmented hepatic glucose production, and heightened insulin resistance." (PMID 38438994, 2024). "Diabetes mellitus (DM) is a chronic metabolic disease characterized by elevated blood glucose levels (hyperglycemia) resulting from defects in insulin secretion, insulin action, or both in the metabolism of carbohydrates, fats, and proteins." (PMID 39857342, 2024). "Diabetes is also closely related to the pancreas, which secretes insulin to regulate blood sugar levels." (PMID 39062777, 2024). "Diabetes therapy now focuses on controlling blood glucose levels through lifestyle changes, oral medicines, and insulin injections." (PMID 38667785, 2024). "Diabetes progression or severity can also be assessed by the use of insulin or the number of oral GLDs used." (PMID 38366387, 2024). "Patients with a BMI ≥ 25 kg/m2, when compared to those with a BMI < 25 kg/m2, were older, had a slightly longer diabetes duration, and were treated with higher insulin doses." (PMID 39335526, 2024). "In subjects with an HbA1c between 9 and 10.9%, there was a significant 215% increase in odds of having an average CRP concentration greater than 0.30 mg/dL when adjusted for demographics, smoking, BMI, fasting insulin level, and length of time with diabetes." (PMID 38999806, 2024). "It was found that the withdrawal of insulin in patients with diabetes mellitus elevated plasma vasopressin concentration, whereas the administration of AVP elicited hyperglycemia, which was associated with the stimulation of the sympathetic system." (PMID 38279313, 2024). "We therefore expected that cortical thickness changes would be explained by the principal characteristics of diabetes (e.g., disease duration, HbA1C, insulin resistance, fasting glucose)." (PMID 39081608, 2024). "Oleanolic acid can also mitigate oxidative stress, with the potential to target diabetes, improving insulin signalling and sensitivity with better glucose homeostasis, among other effects." (PMID 39456465, 2024). "The traditional streptozotocin-induced diabetic mouse model involves the destruction of insulin-producing cells, which results in diminished insulin secretion and the onset of diabetes." (PMID 38448948, 2024). "In diabetes, gene therapy has been widely studied for restoring insulin production in pancreatic cells or transfecting insulin genes into other cells, such as the liver, adipocytes, and muscles, with the aim of inducing production of insulin." (PMID 39000136, 2024). "Diabetes is characterized by impaired metabolism of carbohydrates, proteins, and fats due to insufficient insulin production, insulin resistance, or both." (PMID 38807798, 2024). "Diabetes is a chronic disease that arises when the β-cells in the pancreas fail to produce sufficient insulin or when the body cannot effectively use the insulin it generates." (PMID 38405158, 2024). "Ongoing improvements in SMBG/CGM analytics, insulin injection technology, and data management have evolved into a novel modern form of diabetes treatment alongside education/counseling and adequate drug therapy." (PMID 38572446, 2024). "In 12 months of observation, diabetes requiring insulin therapy occurred in the HIL group at a rate of 19%, while in the rest of the patients, the rate was 27%, p = 0.526." (PMID 38474169, 2024). "Unadjusted analyses demonstrated higher cfPWV was associated with longer diabetes duration, higher age, HbA1c, MAP, and liver stiffness, and lower time-in-range and insulin sensitivity." (PMID 40302945, 2024).